SIRT7 (sirtuin 7)
Diseases named in the same sentence as SIRT7 in open-access papers (continued):
Sharing a sentence is not in itself a finding about the gene and the disease.
breast carcinoma (continued). "In MCF-7 breast cancer cells, SIRT7 inhibition promotes stress resistance, downregulates insulin receptor (INSR), and modulates insulin-like growth factors (IGFs) pathways affecting cell metabolism and growth." (PMID 35328633, 2022). "In contrast, HDAC8 forms a complex with SMAD3/4, in order to transcriptionally suppress SIRT7 and thus inhibit metastasis, increasing the efficacy of chemotherapy in breast cancer." (PMID 33803458, 2021). "GSK3β KD counteracted the stabilization of SIRT7 induced by ERK2 silencing in MDA-231 breast cancer cells and A549 lung cancer cells." (PMID 34433808, 2021). "Analysis of mammary tumors generated in PyMT;Sirt7-TG mice aged 3 months showed a significant decrease in tumor number and tumor burden compared with those generated in the PyMT;WT littermates." (PMID 34433808, 2021). "Similar to our findings, a recent report demonstrated the role of SIRT7 in promoting MET in breast cancers through SMAD4 deacetylation mediated suppression of Slug and Zeb1 transcription." (PMID 32656073, 2020). "The results showed that the expression of SIRT7 mRNA in the breast cancer group was higher than that in the normal group." (PMID 32528869, 2020). "Although SIRT7 expression is associated with poor prognosis in some cancers, such as colorectal cancer, the effect of SIRT7 expression on the prognosis of breast cancer subtypes is unclear." (PMID 32528869, 2020). "HDAC8 was demonstrated to form complex with SMAD3/4 and transcriptionally suppresses SIRT7 thereby reduce metastasis and increase chemotherapy efficacy in breast cancer." (PMID 33193750, 2020). "An analysis of subclass showed that SIRT7 was higher expressed in different subclasses than that in normal breast tissues (normal vs. breast cancer-luminal, p < 10−12; normal vs. HER2-positive breast cancer, p < 10−6; normal vs. TNBC, p < 10−12)." (PMID 32528869, 2020). "SIRT7 showed strong expression in most breast cancer-luminal subtype samples, and few samples showed moderate expression." (PMID 32528869, 2020). "The results showed that the expression levels of SIRT7 were correlated with most markers of different immune cells in breast cancer subtypes (breast cancer-luminal, n = 611; breast cancer-basal, n = 139; breast cancer-HER2+, n = 67)." (PMID 32528869, 2020). "We also evaluated the relationship between SIRT7 expression levels and different clinical pathological parameters of breast cancer, such as sample type, patient's age, cancer stage, and breast cancer subclass." (PMID 32528869, 2020). "Our recent works have demonstrated that SIRT7 reduced breast cancer metastasis via inhibiting the TGF-β signaling." (PMID 33193750, 2020). "TCGA data revealed that SIRT7 mRNA was significantly higher in breast cancer tissues (1,085 cases) than that in normal tissues (112 cases) (p < 0.01), which is consistent with the TIMER database." (PMID 32528869, 2020). "Taken together, these findings suggest that SIRT7 expression is related to the immune infiltration levels in breast cancer, especially breast cancer-luminal, providing a direction for further research." (PMID 32528869, 2020). "The expression of SIRT7 in breast cancer samples was significantly higher than that in normal breast tissues (p < 10−12)." (PMID 32528869, 2020). "Some reports have indicted SIRT7 as an important regulator of TGF-β signaling and an inhibitor of breast cancer metastases and that its deficiency can promote the metastasis of breast cancer cells." (PMID 31817470, 2019). "We have previously shown that SIRT7 participates in breast cancer cell proliferation, migration, and tumor progression by activating p38MAPK." (PMID 31285783, 2019). "Resveratrol treatment inhibits breast cancer and lung metastasis, and increases survival by activating SIRT7." (PMID 30761005, 2019).
breast carcinoma (continued). "We recently demonstrated that SIRT7 deficiency activates TGF-β signaling, enhances EMT and promotes lung metastasis, and induces mesenchymal-like CSCs marked with CD44+CD24- in breast cancers, providing a proof of concept of aging-promoted CSC induction." (PMID 30038266, 2018). "SIRT7 knockdown promoted TGF-β-mediated EMT transition and was blocked by Alk5 inhibitor A8301 in T47D cells, further implicating that SIRT7-regulated breast cancer invasive and migratory ability was TGF-β-dependent." (PMID 28827661, 2017). "Together, our discovery provides new insight for TGFβ regulation during breast cancer metastasis, and we believe SIRT7 belongs to the key regulators that specifically targets breast cancer lung metastasis." (PMID 28827661, 2017). "Consistent with the murine and clinical data, SIRT7 level is inversely correlated with metastatic capacity of various breast cancer cell lines." (PMID 28827661, 2017). "Collectively, these data implicate an essential role of SIRT7-SMAD axis in breast cancer lung metastasis." (PMID 28827661, 2017). "Compared with mock-treated cells, SMAD4 protein level was significantly increased in various breast cancer cells with SIRT7 KD." (PMID 28827661, 2017). "Here the authors report the role of SIRT7 in inhibiting SMAD4-mediated breast cancer metastasis providing a possible therapeutic avenue." (PMID 28827661, 2017). "SIRT7 is downregulated during metastasis, and predicts lung metastasis-free survival of breast cancers." (PMID 28827661, 2017). "Our data highlight SIRT7 as a modulator of transforming growth factor-β signaling and suppressor of breast cancer metastasis, meanwhile providing an effective anti-metastatic therapeutic strategy." (PMID 28827661, 2017). "SIRT7 protein was predominantly stained in nucleus and progressively declined during breast cancer progression." (PMID 28827661, 2017). "To further gain in vivo evidences supporting the connection between SIRT7 and breast cancer metastasis, we employed the polyomavirus middle T antigen (PyMT) transgenic mice, a well-investigated breast cancer model with high risk of lung metastasis." (PMID 28827661, 2017). "Here we show that protein deacetylase SIRT7 is significantly downregulated in breast cancer lung metastases in human and mice, and predicts metastasis-free survival." (PMID 28827661, 2017). "However, the precise mechanism by which kaempferol exerts therapeutic effects in breast cancer, potentially through the modulation of SIRT7‐mediated MCM6‐Kcr, remains to be fully elucidated." (PMID 39477811, 2025). "Additionally, in luminal breast cancer, the positive correlation between SIRT7 expression and the exhaustion marker PD-1 suggests a potential role for SIRT7 in restraining tumor-directed immune responses." (PMID 41471367, 2025). "This pattern implies that SIRT7 might wield distinct functions across various stages of breast cancer progression." (PMID 38383727, 2024). "SIRT7 downregulation promotes breast cancer metastasis by increasing TGF-β signaling; this effect can be reversed by resveratrol treatment, which activates SIRT7 and promotes deacetylation of SMAD4, a central mediator of TGF-β signaling, thereby increasing cancer patient survival." (PMID 37676263, 2024). "SIRT7 employs an additional mechanism to inhibit AKT signaling in breast cancer cells." (PMID 38383727, 2024). "Conversely, a subsequent investigation revealed that the repression of SIRT7 may trigger breast cancer metastasis." (PMID 38316768, 2024). "Moreover, SIRT7 also has the potential to regulate angiogenesis through TGF-β signaling pathway in breast cancer." (PMID 39519130, 2024). "Additionally, SIRT7 interacts with LAP2α in breast cancer, and inhibition of the SIRT7/LAP2α axis represents a potential therapeutic strategy for preventing breast cancer metastasis." (PMID 38894712, 2024).
breast carcinoma (continued). "Similarly to breast cancer, in these tumors, SIRT7 inhibits migration and metastasis formation by deacetylating and inhibiting SMAD4, thus reducing EMT." (PMID 38383727, 2024). "Studies demonstrated that depletion of SIRT7 within breast cancer cell lines yields significant reductions in both proliferation and migration rates in vitro and in vivo, an effect at least partially attributed to the activation of the p38 MAPK signaling cascade." (PMID 38383727, 2024). "Here, our data showed that SIRT7 knockdown promoted CIN in breast cancer cells, as evidenced by compromised DNA repair capacity, increased number of cytoplasmic micronuclei, increased formation of multipolar spindles and downregulated expression of genes that maintain chromatin stability." (PMID 37056924, 2023). "Additionally, our data demonstrated that DOX promoted the metastatic ability of breast cancer cells, implying exploration of the relationship between SIRT7 downregulation and enhanced CIN and metastasis in breast cancer cells." (PMID 37056924, 2023). "Indeed, when we knocked down SIRT7 in breast cancer cells, abnormal changes in nuclear size and morphology that favored CIN were observed." (PMID 37056924, 2023). "Given the crucial role of SIRT7 in maintaining genome stability and the close association between CIN and tumor metastasis, we hypothesized that SIRT7 dysregulation in breast cancer may potentiate metastasis by decreasing genomic stability." (PMID 37056924, 2023). "Co-IP experiments showed that the SIRT7 antibody could pull down LAP2α protein in different breast cancer cells." (PMID 37056924, 2023). "In breast cancer, SIRT7 deacetylates and promotes β-TrCP1-mediated SMAD4 degradation." (PMID 37691108, 2023). "In addition, we observed a positive correlation between SIRT7 and LAP2α expression in clinical breast cancer samples." (PMID 37056924, 2023). "To determine whether there is a causal link between CIN-induced SIRT7 downregulation and CIN-promoted CIN in breast cancer cells, we knocked down SIRT7 with shRNA and siRNA." (PMID 37056924, 2023). "SIRT7 functions as a tumor suppressor to antagonize breast cancer lung metastasis." (PMID 37691108, 2023). "Furthermore, our Co-IP results indicated a direct interaction between SIRT7 and LAP2α in breast cancer cells, in which SIRT7 knockdown increases the ubiquitination and degradation of LAP2α protein and consequently leads to a decreased protein level of LAP2α." (PMID 37056924, 2023). "To investigate whether SIRT7 promotes breast cancer metastasis through the SIRT7/LAP2α axis, we assessed cell migration changes after the knockdown or overexpression of SIRT7 and LAP2α using scratch and transwell assays, respectively." (PMID 37056924, 2023). "However, further studies are needed to clarify the molecular mechanism by which SIRT7 in regulates chromosomal stability and breast cancer cell metastasis." (PMID 37056924, 2023). "There are conflicting reports on the function of SIRT7 in breast cancer." (PMID 36291902, 2022). "miR-3666 inhibits breast cancer cell proliferation by targeting SIRT7." (PMID 35087589, 2022). "Taken together, the authors demonstrated a tumor-suppressing role of SIRT7 in breast cancer." (PMID 36291902, 2022). "Finally, SIRT7 reduces breast cancer metastasis by degrading SMAD4, the key factor in TGF-β pathway, thus inhibiting this pathway." (PMID 33803458, 2021). "Besides, SIRT7 has been shown to be overexpressed in the early stages of breast cancer and diminished gradually later on." (PMID 33498521, 2021).
breast carcinoma (continued). "Indeed, a markedly increased SIRT7 expression was observed when EGF signaling activity was blocked in MDA-231 breast cancer cells by erlotinib, whereas EGF stimulation accelerated SIRT7 protein turnover." (PMID 34433808, 2021). "Correlation analysis between SIRT7 and relate genes and markers of immune cells in breast cancer." (PMID 32528869, 2020). "Relationship between mRNA expression of SIRT7 and clinicopathological parameters of breast cancer." (PMID 32528869, 2020). "Furthermore, SIRT7 is also suggested to serve as a prognostic biomarker in breast cancer based on previous studies." (PMID 33193750, 2020). "Elevated SIRT7 expression is observed in breast cancer, thyroid tumorigenesis, and colon cancer." (PMID 32019578, 2020). "SIRT7 is also a potential prognostic factor for breast cancer." (PMID 32528869, 2020). "We examined the expression levels of SIRT7 in breast cancer using TIMER, GEPIA, and HPA databases." (PMID 32528869, 2020). "In breast cancer, SIRT7 could significantly downregulate SMAD4 protein by deacetylating and destabilizing SMAD4 protein without affecting its mRNA level." (PMID 32019578, 2020). "Therefore, we showed that SIRT7 expression is significantly related to tumor purity in different breast cancer subtypes." (PMID 32528869, 2020). "However, the expression levels of SIRT7 were only significantly negatively correlated with two gene markers in breast cancer-luminal, such as VSIG4 (r = −0.108, p = 1.16e-02) and BDCA-1 (r = −0.114, p = 7.69e-03)." (PMID 32528869, 2020). "Some studies reported that age at diagnosis was an independent prognostic factor for breast cancer, especially for breast cancer-luminal A. However, the correlation between age and SIRT7 expression remains unclear." (PMID 32528869, 2020). "Moreover, we investigated the correlation between SIRT7 expression and immune infiltration levels in breast cancer by TIMER database and immunohistochemistry." (PMID 32528869, 2020). "Previous research has shown that SIRT7 plays the role of a tumor promotor in various cancers, such as epithelial prostate carcinoma, gastric cancer, hepatic cancer, cholangiocarcinoma, ovarian cancer and breast cancer." (PMID 31817470, 2019). "SIRT7 was found overexpressed and upregulated in several tumors, including ovarian cancer, colorectal cancer, osteosarcoma, prostate cancer, breast cancer, and HCC." (PMID 30761005, 2019). "Our findings could inspire the development of drugs that selectively target SIRT7 in breast cancer metastasis, with potential anti-aging benefits." (PMID 28827661, 2017). "Remarkably, SIRT7 was dramatically downregulated in lung metastases in comparison to paired primary tumors in 5 out of 7 patients, suggesting a strong correlation between SIRT7 and human breast cancer lung metastasis." (PMID 28827661, 2017). "Collectively, these findings support an inhibitory role of SIRT7 in breast cancer lung metastasis." (PMID 28827661, 2017). "SIRT7 was inversely correlated with poor prognosis in breast cancers." (PMID 28827661, 2017). "SIRT7 KD increased mesenchymal traits in T47D and 4T1 breast cancer cells." (PMID 28827661, 2017). "In addition ovarian and breast cancer cells showed high levels of SIRT7 and reducing SIRT7 downregulated cancerous cell growth and impacts apoptotic related proteins (NF-kB)." (PMID 28197299, 2017). "Indeed, we found strong expression of SIRT7 in primary tumor site, and in primary breast cancer cell lines." (PMID 28827661, 2017). "Levels of SIRT7 expression were significantly increased in breast cancer (P<0.0001)." (PMID 17003781, 2006). "In this study, we have shown that increased SIRT7 expression is also observed in breast cancer, and may therefore be postulated, in a similar manner, to be required for malignant transformation." (PMID 17003781, 2006). "The observation that SIRT7 is increased in breast cancer tissue compared to normal breast tissue suggests that it may be related to breast cancer tumorigenesis." (PMID 17003781, 2006).
breast carcinoma (continued). "Therefore, SIRT7 may exert anti-tumorigenic functions in breast cancer by controlling these pathways in response to specific dietary regimens." (PMID 38383727, 2024). "Collectively, this evidence strongly indicates that the SIRT7-AKT axis could serve as a pivotal signaling cascade underpinning the advantageous outcomes of tailored dietary regimens in combination with chemotherapy for breast cancer." (PMID 38383727, 2024). "Furthermore, our data demonstrate an enhanced metastatic phenotype of breast cancer metastasis cells when LAP2α protein is knocked down and degraded due to SIRT7 knockdown, and LAP2α overexpression significantly reversed the change in the metastatic phenotype induced by SIRT7 knockout." (PMID 37056924, 2023). "However, the prognosis of SIRT7 in different breast cancer subtypes and its correlation with tumor-infiltrating lymphocytes remain unclear." (PMID 32528869, 2020). "Therefore, we investigated whether the expression of SIRT7 was correlated with the immune infiltration levels in breast cancer using TIMER." (PMID 32528869, 2020). "However, the relationship between SIRT7 and immune infiltration in breast cancer-luminal remains unclear." (PMID 32528869, 2020). "Interestingly, EMT-type CSCs (CD44+) are associated with low SIRT7 and share similar set of genes with OCT3/4, suggesting differential roles of Sirtuins on breast cancer stemness: SIRT1 is related to MET-type CSCs (ALDH1+), whereas SIRT7 is correlated with EMT-type (CD44+)." (PMID 30038266, 2018). "Moreover, we found SIRT7 deficiency does not affect the proliferation capacity of in vitro cultured breast cancer cells, but promotes in vivo tumor growth in xenograft models." (PMID 28827661, 2017). "SIRT7 can inhibit metastasis of breast cancer by inhibiting TGF-β signaling, and HDAC8 can suppress the expression of SIRT7 to promote cancer cell survival and migration." (PMID 40165290, 2025). "In breast cancer cells, FK506 binding protein 51 (FKBP51), a member of the FKBPs, is deacetylated and activated by SIRT7." (PMID 39519130, 2024). "In another scenario, SIRT7 interacts with EST-1 transcription factor and subsequently deacetylates histone at the TEK promoter, thereby inhibiting breast cancer metastasis." (PMID 37676263, 2024). "Indeed, a survival analysis conducted on breast cancer patients using the Cbioportal database reveals a significant correlation between low expression of SIRT7 and unfavorable patient outcomes, supporting a role of SIRT7 as a tumor suppressor in this cancer type." (PMID 38234684, 2023). "In the present study, our data demonstrated that DOX treatment inhibited SIRT7 expression and enhanced CIN and metastasis in breast cancer cells." (PMID 37056924, 2023). "The authors further demonstrated that miR-3666 targets the SIRT7 3′-UTR, and miR-3666 overexpression reduces the expression of SIRT7, resulting in increased proliferation and reduced apoptosis of breast cancer cells." (PMID 36291902, 2022). "Recently, an important study showed that SIRT7 deacetylates FKBP51 to promote the PHLPP-mediated dephosphorylation of AKT at Ser473, which sensitizes breast cancer cells to chemotherapy." (PMID 34433808, 2021). "In addition, miR 125a-5p could increase SIRT7 and also raised apoptosis in lung cancer cells to rise their radiosensitivity and miR-22 suppresses cancerogenesis and enhances radiosensitivity of breast cancer cells by selecting SIRT1, supplying a hopeful therapeutic objective for breast cancer." (PMID 33705642, 2021). "We found that the expression of SIRT7 was positively correlated with the expression of IRF5 (M1 macrophages marker) and PD1 (PDCD1) (T cell exhaustion marker) in breast cancer-luminal." (PMID 32528869, 2020). "SIRT7 was found to suppress EMT in oral squamous cells, carcinoma cells, and breast cancer cells by promoting SMAD4 deacetylation, leading to increase of E-cadherin and down regulation of N-cadherin and Vimentin." (PMID 32656073, 2020).